PAX7 (paired box 7)
Diseases named in the same sentence as PAX7 in open-access papers (continued):
Sharing a sentence is not in itself a finding about the gene and the disease.
muscular dystrophy (7 papers, 2016 to 2023). Muscular dystrophy (MD) refers to a group of more than 30 genetic diseases characterized by progressive weakness and degeneration of the skeletal muscles that control movement. "Muscular dystrophies, despite their different underlying causes, share a common characteristic of progressive muscle wasting, in which Pax7 could play a crucial role." (PMID 37685856, 2023). "Of these 30 GOSC genes selected on the basis of involvement in satellite cell biology, only 4 are also included in the 116 myopathogenes, so known to cause muscular dystrophies/myopathies when mutated: these are PAX7, MEGF10, SELENON (formerly SEPN1) and CAPN3." (PMID 34740639, 2022). "By understanding and harnessing Pax7’s regulatory potential, we can enhance current therapeutic efforts and pave the way for more effective treatments for various forms of muscular dystrophy." (PMID 37685856, 2023). "Realistically, relying solely on Pax7 as a therapeutic target in muscular dystrophy treatment would be challenging, due to the diverse forms of muscular dystrophy and their respective genetic mutations." (PMID 37685856, 2023). "Utilizing Pax7’s regulatory function could be advantageous, particularly in combination with existing approaches in muscular dystrophy therapy." (PMID 37685856, 2023). "CD82/Pax7-positive target populations might have translational potential for CRISPR/Cas9-mediated editing in the context of muscular dystrophies, insofar as HDR in differentiated skeletal muscle remains challenging." (PMID 38020204, 2023). "Furthermore, it would be essential to investigate whether muscular dystrophy models undergoing treatment via pharmacological strategies could benefit from the regenerative potential of Pax7 overexpression when induced." (PMID 37685856, 2023). "We deploy transcriptomic analysis and comparison between muscular dystrophies and myopathies to determine the contribution of satellite cell dysfunction using literature, expression dynamics of myopathogenes and their response to the satellite cell regulator PAX7." (PMID 34740639, 2022). "Additionally, while Pax7 shows promise as a valuable player in mitigating muscle wasting, it is more practical to view it as part of a comprehensive approach in combination with other therapeutic strategies, for addressing the complexities of muscular dystrophy effectively." (PMID 37685856, 2023). "However, when it comes to muscular dystrophy, there is a lack of information regarding Pax7’s specific role at various stages of the disease progression." (PMID 37685856, 2023).
Duchenne muscular dystrophy (6 papers, 2017 to 2025). Duchenne muscular dystrophy (DMD) is a neuromuscular disease characterized by rapidly progressive muscle weakness and wasting due to degeneration of skeletal, smooth and cardiac muscle. "An increased number of Pax7-positive cells has also been observed in the muscle of patients with Duchenne muscular dystrophy and dystrophin-deficient mdx mice." (PMID 41397955, 2025). "We found that myogenic cells derived from extra eyelid tissue proliferated and differentiated myofibers in vitro, and restored DYSTROPHIN or PAX7 expression after transplantation with these cells in mice with Duchenne muscular dystrophy." (PMID 31337111, 2019). "Transplantation of Pax7-positive cells into mdx mice, the animal model of Duchenne muscular dystrophy (DMD), led to the appearance of dystrophin, a protein which is not present in DMD muscle, causing myofiber membrane fragility and muscle injuries." (PMID 31412558, 2019). "Interestingly, it has been revealed that overexpression of Pax7 regulates myogenic differentiation by downregulating MyoD expression and prevents MyoG induction in fetal Duchenne Muscular Dystrophy (DMD) muscle tissues, suggesting a delay in myofibers differentiation program." (PMID 37685856, 2023).
cleft lip (5 papers, 2021 to 2025). Congenital defect in the upper lip where the maxillary prominence fails to merge with the merged medial nasal prominences. "Several genome-wide associations (GWA) studies have shown the association of the paired box 7 (PAX7) gene in the etiology of cleft lip and palate in different populations worldwide." (PMID 35846106, 2022). "PAX7 is more associated with the formation of unilateral cleft lip, while PAX9 relates more towards the isolated cleft palate." (PMID 34684112, 2021). "PAX7 gene polymorphisms have been significantly associated with cleft lip and palate in a genome wide population association studies." (PMID 33917041, 2021). "For PAX7 in bilateral cleft lip affected tissue, the median number of PAX7-positive epiheliocytes was moderate (++) and the number of factor-positive epitheliocytes ranged from a few (+) to numerous (+++) PAX7-positive cells." (PMID 34684112, 2021). "The Mann–Whitney U test notified a statistically significant difference in the number of PAX7-positive epitheliocytes in the epithelium between the control group and unilateral cleft lip affected tissue group (U = 5.5, p = 0.001)." (PMID 34684112, 2021). "Thus, our results are partially in line with another research, where authors observed statistically important differences in PAX7 distribution in the epithelium and connective tissue of unilateral cleft lip in immunohistochemically stained tissue." (PMID 38227085, 2024). "The Kruskal–Wallis H test also indicated a statistically significant difference in the number of PAX7-positive structures in the connective tissue between the controls, unilateral cleft lip, bilateral cleft lip, and isolated cleft palate groups (H = 28.955, df = 3, p < 0.001)." (PMID 34684112, 2021). "Transcription factors PAX7 and PAX9 are variably involved in the postnatal morphopathogenesis of different facial cleft types: PAX7 is stably associated with the formation of unilateral cleft lip, while PAX9 relates more towards the isolated cleft palate." (PMID 34684112, 2021). "The use of the Kruskal–Wallis H test notified that a statistically significant difference was found in the number of PAX7-positive structures in the epithelium between the controls, unilateral cleft lip, bilateral cleft lip, and isolated cleft palate groups (H = 25.804, df = 3, p < 0.001)." (PMID 34684112, 2021). "The aim of this study was to detect and compare the immunohistochemical expression of cleft candidate gene coded proteins (DLX4, MSX2, HOXB3, SHH, PAX7, SOX3, WNT3A, and FOXE1) in the non-syndromic unilateral cleft lip patient tissue and control group tissue." (PMID 33917041, 2021). "Multiple statistically significant moderate correlations were found between PAX7, PAX9, and RYK within the unilateral cleft lip and isolated cleft palate affected tissue." (PMID 34684112, 2021). "Similarly, a strong correlation between PAX7-positive epitheliocytes in the epithelium and RYK-positive structures in the epithelium was found in isolated cleft palate affected tissue, but in unilateral cleft lip affected tissue this correlation was only moderate." (PMID 34684112, 2021). "The available literature strongly indicates PAX7, PAX9, SHH, SOX3, WNT3A, and WNT9B to be strong candidate genes for cleft lip with or without cleft palate." (PMID 38227085, 2024).
facioscapulohumeral muscular dystrophy (5 papers, 2017 to 2026). An autosomal dominant disorder affecting the skeletal muscles of the face, scapula, and upper arm. "In this review CRS Banerji and PS Zammit discuss the relationship between transcription factors DUX4 and PAX7 in the pathology of facioscapulohumeral muscular dystrophy." (PMID 34151531, 2021). "Similarly, in Facioscapulohumeral muscular dystrophy, inducing Pax7 overexpression in regions where it is repressed might hold the potential to ameliorate disease pathology." (PMID 37685856, 2023). "Recent studies have described the functions of Pax7 in muscle diseases: PAX7-target genes are globally repressed by the DUX4 transcription factor, which is ectopically expressed in muscles of facioscapulohumeral muscular dystrophy (FSHD) patients." (PMID 30139390, 2018).
glioblastoma (5 papers, 2015 to 2026). The most malignant astrocytic tumor (WHO grade IV). "PTEN deficiency leads to the upregulation of PAX7, which in turn promotes oncogenic transformation of NSCs and instates ‘aggressiveness' in human glioblastoma stem cells." (PMID 26632666, 2015). "CNS neural progenitor marker Pax7 also becomes upregulated in glioblastoma with PTEN deficiency." (PMID 35538578, 2022). "However, PTEN deficiency leads to upregulation of PAX7, which in turn promotes oncogenic transformation of human neural stem cells and confers aggressiveness to human glioblastoma stem cells." (PMID 36411429, 2022). "In a large clinical database, we find increased PAX7 levels in PTEN-deficient glioblastoma." (PMID 26632666, 2015). "When PTEN is lost in human neural stem cells, there is an increase in phosphorylated CREB (cyclic AMP response element binding protein) leading to increased PAX7 transcription and ultimately a more glioblastoma-like cell state." (PMID 36830628, 2023).
melanoma (5 papers, 2011 to 2025). A malignant, usually aggressive tumor composed of atypical, neoplastic melanocytes. "Overexpression of both genes has been implicated in melanoma and both received high scores by the prediction programs, with PAX7 ranked first according to consensus prediction of the three algorithms." (PMID 22096567, 2011). "Since melanocytes share a common embryonic origin with neural crest cells, pathways involving PAX7 and Elk3 may play a role in melanoma progression." (PMID 39404397, 2024). "Moreover, PAX7 and Elk3 are significant in the context of melanoma and neuroblastoma, both of which originate from neural crest-derived cells." (PMID 39404397, 2024). "In melanoma, PAX7 dysregulation can influence melanocyte development and transformation." (PMID 39404397, 2024). "Abnormal PAX7 activity could lead to unchecked proliferation and the survival of melanocyte precursors, contributing to melanoma." (PMID 39404397, 2024). "On the other hand, enforced expression of TAF4 promoted expression of pluripotency- associated KLF4, OCT4 and NANOG, and NC-related MSX2, PAX7, SOX10 and SNAI1, reaffirming the critical role of hTAF4-TAFH activity in the maintaining of multipotency in melanoma cells." (PMID 27499390, 2016).
Ewing sarcoma (4 papers, 2021 to 2025). A small round cell tumor that lacks morphologic, immunohistochemical, and electron microscopic evidence of neuroectodermal differentiation. "The regulatory network analysis sheds light on the Ewing Sarcoma regulatory behavior by identifying PAX7 and RUNX3 as promising master regulators for this cancer." (PMID 33924679, 2021). "Additionally, nuclear PAX7 positivity is expressed in a majority of Ewing sarcomas." (PMID 40255709, 2025).
ischemia (4 papers, 2019 to 2025). A hypoperfusion of the BLOOD through an organ or tissue caused by a PATHOLOGIC CONSTRICTION or obstruction of its BLOOD VESSELS, or an absence of BLOOD CIRCULATION. "AT-derived EVs benefit skeletal muscletrophism, protecting against ischemic degeneration and enhancing regeneration ina hindlimb ischemia model via increased MyoD, Myf5, and Pax7 expression." (PMID 39916853, 2025). "Collectively, these data demonstrate that Pax7+ MPCs are required for muscle regeneration after ischemia and suggest that muscle regeneration may be an important therapeutic target in PAD." (PMID 36937923, 2023). "As hypothesized, we observed a substantial increase in quiescent Pax7+ MuSC content at days 7 and 14 following ischemia, with a peak at day 7 that accompanies the accretion of myonuclei and a concomitant decrease in the myonuclear domain." (PMID 31266969, 2019). "Therefore the decreases miR-206 levels and increases expression of Pax7 following ischemia may affect the adaptive response to resistance exercise." (PMID 35396528, 2022).
metastatic disease (4 papers, 2014 to 2025). "In metastatic disease, patients with PAX7::FOXO1 aRMS were significantly younger compared to PAX3::FOXO1 positive group (68% vs. 33% of patients ≤10 years of age), all other factors were similarly distributed." (PMID 39781573, 2025). "Interestingly, while fusion subtype does not affect survival of patients presenting without clinically overt distal metastases, patients presenting with PAX3/FOXO1 metastatic disease appear to have worse outcomes than those with PAX7/FOXO1 metastatic disease." (PMID 32697014, 2020). "Pairwise analysis between Non‐Hispanic Black versus Non‐Hispanic White patients and Hispanic versus Non‐Hispanic White patients for age group, RMS histology, Intergroup Rhabdomyosarcoma Study (IRS) group, tumor invasiveness, metastatic disease, and FOXO1 fusion partner (PAX3 or PAX7)." (PMID 37081771, 2023). "Among patients with metastatic disease, patients aged >10 years, with FP tumors, PAX3::FOXO1 fusion type and B/BM involvement, had significantly worse EFS and OS compared to patients aged ≤10 years, without B/BM involvement, FN tumors, or with PAX7::FOXO1 fusion type." (PMID 39781573, 2025).
neuroblastoma (4 papers, 2015 to 2024). Neuroblastoma (NB) is the most common solid, extracranial childhood tumor. "The dysregulation of PAX7 can affect neuroblastoma cell behavior, and the retention of Pax7+ precursors due to Elk3 loss suggests that disruptions in these pathways could contribute to neuroblastoma pathology, where progenitor cells fail to differentiate properly." (PMID 39404397, 2024). "On the other hand, neuroblastoma, a cancer originating from neural crest-derived cells in the sympathetic nervous system, is also related to the roles of PAX7 and Elk3." (PMID 39404397, 2024). "In this study, Pax3 and Pax7 genes were overexpressed in Neuro‐2a, the mouse neuroblastoma cell line." (PMID 33336498, 2021).
oculopharyngeal muscular dystrophy (4 papers, 2015 to 2025). Oculopharyngeal muscular dystrophy (OPMD) is an adult-onset progressive myopathy characterized by progressive eyelid ptosis, dysphagia, dysarthria and proximal limb weakness. "In addition, let-7-targeting paired cassette 7 (PAX7) and IL-6 in senescent muscle and oculopharyngeal muscular dystrophy (OPMD), a disease that shares molecular characteristics with senescent muscle, leads to reduced muscle regeneration and functional degeneration." (PMID 36008964, 2022).
Atrophy (3 papers, 2016 to 2026). Any weakening or degeneration, especially through lack of use. "Furthermore, muscle stem cell number was reduced in the patients with diaphragm atrophy (PAX7 positive nuclei per myofiber of 0.10 [0.09-0.11] vs. 0.05 [0.04-0.07], p = 0.002 in control patients and ICU patients with atrophy, respectively)." (PMID 41693227, 2026).
Diabetes (3 papers, 2021 to 2026). "The role of SYP, BDNF, and PAX7 in memory and the effect of diabetes on the reduction of these genes have been reported in several studies." (PMID 37970442, 2023). "Diabetes in DC group was accompanied with decreased number of Pax7 positive cells significantly in the gastrocnemius muscle compared to the C group (p < 0.001)." (PMID 33953268, 2021). "Diabetes increases the reactive oxygen species (ROS) level in cells and changes the expression of several genes, including SYP, BDNF, PAX7, and SYNCAM1, through the FOXO transcription factor." (PMID 37970442, 2023). "In the present study, we investigated the effects of diabetes on the structural damage of the cerebellum and memory-related (SYP, BDNF, PAX7, and SYNCAM1) genes." (PMID 37970442, 2023). "In the present study, we tried to investigate the effects of diabetes on the structural and functional damage of the cerebellum and memory-related genes, including SYP, BDNF, and PAX7 genes in the cerebellum." (PMID 37970442, 2023). "Therefore, we assessed the effects of diabetes on the expression of FOXO-regulated memory-related genes, including SYP, BDNF, and PAX7 genes in the cerebellum." (PMID 37970442, 2023).
embryonal rhabdomyosarcoma (3 papers, 2015 to 2020). A poorly circumscribed morphologic variant of rhabdomyosarcoma. "Although embryonal rhabdomyosarcoma most likely arises from myoblasts, both markers of quiescent satellite cells, e.g., PAX3, PAX7, or HEYL, and markers of activated satellite cells, including MYOD1, are frequently expressed." (PMID 31941033, 2020). "It was suggested that PAX2 and PAX5 play tumor suppressor roles in ovarian cancer and leukemia, while conversely, PAX3, PAX7, and PAX6 were reported to be oncogenic in embryonal rhabdomyosarcomas and retinoblastoma." (PMID 31235851, 2019).
gastric cancer (3 papers, 2016 to 2023). A primary or metastatic malignant neoplasm involving the stomach. "In both muscles of human gastric cancer patients and mouse of a mouse cancer cachexia model, Pax7 and MyoD mRNA/protein levels were upregulated." (PMID 30300394, 2018). "KTM2A was found to have interactions with MEN1, MLL1 complex, ATR, KAT8, SP11, and PAX7 none of which have been implicated in gastric cancer before." (PMID 37287033, 2023). "A study on the expression of genes involved in muscle regeneration (Pax7, MyoD, Myf5, nMyHC, necdin) in gastric cancer patients found that Pax7 was significantly increased in all disease stages compared to controls, whereas MyoD and necdin were only upregulated in early disease stages." (PMID 26856534, 2016).
glioma (3 papers, 2024 to 2025). A benign or malignant brain and spinal cord tumor that arises from glial cells (astrocytes, oligodendrocytes, ependymal cells). "PTEN loss induces up-regulation of paired box 7 (PAX7), reprogramming NSCs into a glioma stem cell phenotype." (PMID 39935607, 2025). "PTEN in glioma binds to the PAX7 promoter, suppressing PAX7 transcription through interaction with cAMP response element binding protein 1 (CREB)/CREB binding protein (CBP)." (PMID 40370330, 2025).
lung carcinoma (3 papers, 2013 to 2022). "Nonetheless, myogenin was found increased also in human cachectic muscle from patients with lung cancer (where also an increased NF-Kb/PAX7 signaling occurred as in our samples)." (PMID 32824440, 2020). "Of the 42 common Significant hypermethylated genes unique to Stages I and III, GALR1, NID2 have been identified as highly methylated in NSCLC, PAX7 has been identified in lung cancer but not reported with methylation, though PAX family genes have been previously reported being methylated in cancer." (PMID 24369052, 2013).
muscular atrophy (3 papers, 2021 to 2023). The loss of muscle tissue due to inactivity or disease. "In humans, loss‐of‐function PAX7 mutations lead to the congenital muscular dystrophy MYOSCO (OMIM: 618578) with similarities to some cases of early onset FSHD including hypotonia, muscular atrophy, decreased respiratory function and spinal deformities." (PMID 34151531, 2021). "In the current study, in vitro analysis revealed that the expression of Pax-7 markers upregulated the differentiation of skeletal muscle, whereas in vivo analysis revealed that Pax-7 expression levels were significantly lower in the muscular atrophy group than in the control group." (PMID 37963838, 2023). "Next, the effects of treatment with FG-4592 on the progression of skeletal muscle atrophy and on the impairment of the regeneration process were examined by analyzing MURF1 and PAX7, respectively." (PMID 35806119, 2022).